LCN2 (lipocalin 2)
Diseases named in the same sentence as LCN2 in open-access papers (continued):
Sharing a sentence is not in itself a finding about the gene and the disease.
breast tumor (13 papers, 2008 to 2025). "LCN2 is involved in invasion and metastasis, and its expression has been linked to poor prognosis in ER/PR-negative breast tumors." (PMID 18221536, 2008). "In both PyMT-mouse models and human breast tumors, LCN2 expression predominantly occurs in the tumor stroma rather than within tumor cells." (PMID 39188682, 2024). "Deletion of LCN2 significantly inhibited lymphatic vessel growth surrounding tumors and decreased metastasis of breast tumors in both MMTV-PyMT mice and mice with orthotopic wild-type tumors." (PMID 39188682, 2024). "Macrophages supply iron to the breast tumor microenvironment by enforced secretion of lipocalin-2 (Lcn-2)-bound iron as well as the increased expression of the iron exporter ferroportin (FPN)." (PMID 33808732, 2021). "In this study, the LCN2 protein levels were quantified in 28 breast tumors by immunohistochemistry (IHC)." (PMID 32575507, 2020). "In this same study, 109 (44%) of the 250 breast tumors analyzed via Western blot also exhibited the presence of LCN2." (PMID 32575507, 2020). "For example, there are significantly higher levels of LCN2 in breast tumor tissues (stages II–III) compared to normal breast stroma." (PMID 32575507, 2020). "S1P increases the expression of lipocalin 2 (LCN2) in macrophages, resulting in lymphangiogenesis in the breast tumor model." (PMID 29467963, 2018). "Importantly, it was shown that neoadjuvant therapy leads to the upregulation of Lcn-2 in human breast tumors, highlighting the importance of targeting Lcn-2 as an additional therapeutic approach." (PMID 37958332, 2023). "Lipocalin (LCN2), another top up-regulated gene among malignant tumours in our data set, has been shown to be associated with oestrogen receptor (ER)-negative breast tumours in humans." (PMID 30517191, 2018). "As IL-1β and LCN2 appear to promote breast tumour malignancy and lead to a poorer prognosis, we speculate that β-hydroxybutyrate induced upregulation of their expression might contribute to the observed increased tumorigenesis." (PMID 28281525, 2017). "The expression of LCN2 has been demonstrated to enhance breast tumour formation and progression." (PMID 23056397, 2012). "This study aimed to investigate the roles of lipocalin 2 in breast tumor metastasis." (PMID 19077278, 2008). "Our observation of efficient internalization and targeting of LCN2 using siRNA-LCN2-loaded Herceptin-functionalized liposomes builds on these prior studies by evaluating promising innovative therapeutic avenues to inhibit the biological role of LCN2 in breast tumors." (PMID 40732340, 2025). "In both PyMT-mouse tumors and primary human breast tumors, LCN2 is primarily expressed in the tumor stroma rather than in the tumor cells themselves." (PMID 39188682, 2024). "Since TAM may serve as an iron source within the breast tumor microenvironment, we determined the iron amount of TAM isolated from WT and Lcn-2−/− tumors." (PMID 33808732, 2021). "Furthermore, estrogen receptor α (ERα) has been noted to negatively regulate Slug, and a negative correlation was observed between LCN2 expression and the expression of ERα and progesterone receptor (PR) in primary breast tumors." (PMID 39188682, 2024).
chronic obstructive pulmonary disease (13 papers, 2014 to 2025). A chronic and progressive lung disorder characterized by the loss of elasticity of the bronchial tree and the air sacs, destruction of the air sacs wall, thickening of the bronchial wall, and mucous accumulation in the bronchial tree. "IL-17A reportedly promotes increased expression of LCN2 in human neutrophils and remodeling of airway epithelium in patients with chronic obstructive pulmonary disease (COPD)." (PMID 39139502, 2024). "In the lung, increased LCN2 expression has been reported in subclinical pulmonary emphysema, chronic obstructive pulmonary disease (COPD), acute respiratory distress syndrome (ARDS), as well as in patients with influenza A and SARS-CoV-2 virus infections." (PMID 37746070, 2023).
cognitive decline (13 papers, 2019 to 2024). "The positive finding of an association between circulating LCN2 levels and cognitive decline in our study highlights the possible role of LCN2 as a possibly predictor of MCI in patients with MetS." (PMID 35302058, 2022). "In addition, the five-year time span of this cohort study provides more information about the direction of changes of LCN2 levels and its possible direction of association with cognitive decline." (PMID 35302058, 2022). "By immune-staining and Sholl analysis, we found that after surgery, microglia were not changed in cell density in the brain but exhibit a less ramified morphology; by gain and loss of function of LCN2, we revealed that LCN2 mediates surgery-induced microglia activation and cognitive decline." (PMID 35413913, 2022). "By MACS, microglia depletion, gain and loss function of LCN2, combining with in vitro experiments, we demonstrated that LCN2 might serve as a signal from neuron to microglia and contribute to the development of neuroinflammation and cognitive decline." (PMID 35413913, 2022). "LCN2 serves as a key mediator of neuroinflammation and cognitive decline, with astrocytes playing a pivotal role in these processes." (PMID 38991663, 2024). "Our findings suggest that reactive astrocytes in the hippocampus are sufficient and required to induce cognitive decline through LCN2 release and synaptic modulation." (PMID 38991663, 2024). "Lipocalin-2 (LCN2), a pro-inflammatory molecule secreted into the peripheral circulation by neutrophils, is believed to cause cognitive decline." (PMID 37238612, 2023). "On the other hand, this study and an earlier investigation reported significant inverse correlation of CSF Abeta42 with serum LCN2 in patients with subjective cognitive decline and with plasma LCN2 in preclinical AD, respectively." (PMID 35027079, 2022). "Combing with in vitro microglia cell culture, we have studied the role of LCN2 in surgery-induced cognitive decline in mice." (PMID 35413913, 2022). "While the precise molecular mechanisms remain unclear, these findings highlight the intricate role of LCN2 in astrocyte-mediated cognitive decline and suggest potential therapeutic avenues for targeting specific astrocyte activation phenotypes." (PMID 38991663, 2024). "Combined with the data obtained from the optogenetic and chemogenetic stimulation experiments, this inhibitor study suggests that hippocampal CA1 astrocyte activation is sufficient and necessary for LCN2 release, neuroinflammation, and subsequent cognitive decline." (PMID 38991663, 2024). "In the present study, we determined whether LCN2 was involved in neuroinflammation and cognitive decline after the repeated optogenetic stimulation of astrocytes, for which we first evaluated the hippocampal expression of LCN2 after optogenetic stimulation." (PMID 38991663, 2024). "It is unclear how LCN2 contributes to cognitive decline in AD patients." (PMID 37238612, 2023). "In this study, our data demonstrate a neurotoxic potential role of surgery procedure-induced neuronal LCN2, and a single dose of rLCN2 administered intracranially could lead to cognitive decline." (PMID 35413913, 2022). "Moreover, LCN2 is also strongly related to an impaired metabolic state, such as impaired glucose metabolism, thus leading to cognitive decline." (PMID 33945675, 2021). "Therefore, we sought to address the role of LCN2 in surgery-induced cognitive decline." (PMID 35413913, 2022). "Conversely, silencing LCN2 in hippocampus by AAV-shRNA protected mice from surgery-induced microglia morphological changes, neuroinflammation and cognitive decline." (PMID 35413913, 2022). "Freezing time was increased after knocking down of LCN2 when compared with Control-AAV group after surgery, indicating cognitive decline was ameliorated." (PMID 35413913, 2022).
cognitive decline (continued). "Importantly, lipocalin 2 has previously been found to be upregulated in the hippocampus following psychological stress and regulates stress-induced neuronal excitability and anxious behavior, which has been considered as a potential biomarker in aging-related cognitive decline." (PMID 34565419, 2021). "The resultant LCN2 released from the reactive astrocytes decreased the NMDA receptor-mediated synaptic activity, thereby affecting the long-term synaptic plasticity of hippocampal CA1 neurons and resulted in cognitive decline." (PMID 38991663, 2024). "How LCN2 contributes to cognitive decline in AD patients is not fully understood." (PMID 37238612, 2023). "Furthermore, by performing microglia depletion in vivo, we demonstrated that surgery-induced cognitive decline is dependent on the presence of microglia, while LCN2 upregulation was independent of the presence of microglia." (PMID 35413913, 2022).
glioblastoma (13 papers, 2016 to 2025). The most malignant astrocytic tumor (WHO grade IV). "In contrast, resistance to 1, 3-Bis (2-chloroethyl)-1-nitrosourea (BCNU), an alkylating agent commonly used for glioblastoma, was associated with the reduced expression of LCN2 in glioblastoma cells." (PMID 27168162, 2016). "Similarly, in glioblastoma, LCN2 is implicated in resistance to BCNU (carmustine), primarily through its role in Akt dephosphorylation, which is crucial for apoptosis sensitization." (PMID 39188682, 2024). "Lipocalin-2 (LCN2) exhibits pro- and anti-carcinogenic effects in several cancers, but its role in the progression of glioblastoma multiforme (GBM) remains poorly understood." (PMID 34062746, 2021). "This is significant given that dPGS can downregulate LCN2 in neural cells and decrease glioblastoma invasiveness." (PMID 33171886, 2020). "On the other hand, dPGS was internalized into glioblastoma tumoroids and decreased LCN2 levels in glioblastoma cells in vitro." (PMID 33171886, 2020). "In addition, glioblastoma multiforme (GBM) cells overexpressing LCN2 showed significantly decreased proliferation and invasion capacities." (PMID 39139502, 2024). "Downregulation of Lipocalin 2 added the new outcomes in glioblastoma." (PMID 33473259, 2020). "High LCN2 and GFAP levels were also observed in tumor tissues from glioblastoma patients as compared to control brain tissues." (PMID 33171886, 2020). "In glioblastoma models, co-culturing glioblastoma cells with microglia resulted in significantly higher LCN2 levels and increased nuclear NFκB and STAT3 phosphorylation compared to monoculture, suggesting that microglia stimulate glioblastoma through LCN2 modulation." (PMID 39188682, 2024). "Lipocalin-2 (LCN2) exhibits pro- and anti-carcinogenic effects in several cancers, but its role in the progression of glioblastoma multiforme (GBM) remains unclear." (PMID 34062746, 2021). "The genetic alteration profiling of LCN2 showed that its amplification was one of the most important single factors for alteration in ACC, cervical adenocarcinoma, ESCC, PAAD, ovarian epithelial tumor, diffuse glioma, HNSC, HCC, BRCA, glioblastoma, renal non-clear cell carcinoma and PAAD." (PMID 33425761, 2020).
lung adenocarcinoma (13 papers, 2014 to 2025). A carcinoma that arises from the lung and is characterized by the presence of malignant glandular epithelial cells. "However, lung microbiome α-diversity increased following tobacco exposure among mice unable to express the bacterial growth inhibitor lipocalin 2, a component of the innate immune system that is protective against lung adenocarcinoma." (PMID 38500160, 2024). "Tight control of LCN2 expression might be important to prevent the development of epithelial hyperproliferation in inflammatory conditions and lung adenocarcinoma." (PMID 27136530, 2016). "Moreover, inhibition of Matrix Metalloproteinase-9 (MMP-9) by lipocalin 2 (LCN2) can reduce almonertinib resistance, suggesting that the LCN2/MMP-9 axis might offer a potential strategy for addressing drug resistance in lung adenocarcinoma." (PMID 41291696, 2025). "Notably, the miR-200 family and Lipocalin-2 (LCN2) mRNA in exosomes could stratify patients with lung adenocarcinoma from individuals with benign lung disease, suggesting that these two RNAs may serve as potential diagnostic markers for the NSCLC." (PMID 38765006, 2024).
Crohn disease (12 papers, 2010 to 2024). A gastrointestinal disorder characterized by chronic inflammation involving all layers of the intestinal wall, noncaseating granulomas affecting the intestinal wall and regional lymph nodes, and transmural fibrosis. "In SAM enteropathy and in Crohn's disease there was increased expression of DUOX2, DUOXA2, lipocalin 2, CEACAM 5 and 7, MUC1, SAA 1, 2 and 4, and CXCL5 genes, and these transcripts were further over-expressed in HIV infection." (PMID 31229436, 2019). "In addition, fecal Lcn-2 also serves as a marker of intestinal inflammation induced by the enteropathogen Adhesive-Invasive E. coli (AIEC), first isolated from a Crohn’s disease patient." (PMID 22957064, 2012).
esophageal cancer (12 papers, 2009 to 2025). A primary or metastatic malignant neoplasm involving the esophagus. "LCN2 is also implicated in extracellular matrix (ECM) remodeling and metastasis in breast and esophageal cancers, where elevated LCN2 levels correlate with enhanced migratory and invasive capacities of tumor cells." (PMID 40472740, 2025). "Our results showed that an LCN2/LOXL2/MMP9 ternary complex was formed in oesophageal cancer, with a distinctive intracellular and extracellular interaction pattern." (PMID 37753805, 2023). "LCN2, which is methylated at low levels but highly expressed in esophageal cancer, regulates the migration and invasion of esophageal cancer via multiple pathways." (PMID 35989326, 2022). "In this study, we identify the signal transduction pathway of TPA-induced LCN2 expression in esophageal cancer." (PMID 29098164, 2017). "In conclusion, our previous studies have suggested that LCN2 plays a critical role and has a distinctive regulatory mechanism in esophageal cancer." (PMID 29098164, 2017). "The expression of LCN2 was visibly decreased in the GSE26886 esophageal carcinoma expression data, which contradicts previous results." (PMID 26131602, 2015). "NGALR-3 variants generated by alternative splicing in esophageal cancer may act as potential LCN2 receptors and play a role in LCN2-mediated iron transport in esophageal cancer." (PMID 40109857, 2025). "Therefore, the LCN2/LOXL2/MMP9 ternary complex can promote the invasion of oesophageal cancer cells by elevating the expression of MMPs to degrade gelatin and fibronectin." (PMID 37753805, 2023). "We showed that DFOM inhibited the migration and invasion of oesophageal cancer cells through multiple mechanisms, including reducing the expression of LCN2 and LLM, suppressing MMP9 enzyme activity, inhibiting cytoskeletal rearrangement, and thus restoring ECM remodelling." (PMID 37753805, 2023). "This suggested that the ternary complex of LCN2/LOXL2/MMP9 existed in oesophageal cancer cells." (PMID 37753805, 2023). "To verify whether LCN2 was downregulated at the protein level in esophageal cancer cells, we treated cancer cells with different concentrations of CUDC-907 and performed western blot analysis, showing that LCN2 was considerably decreased at the protein level." (PMID 35989326, 2022). "More importantly, CUDC-907 could downregulate LCN2 expression in esophageal cancer cell lines, leading to ROS accumulation, ultimately activating cytotoxic autophagy through ER stress pathway, followed by programmed cell death." (PMID 35989326, 2022). "The role of LCN2 in esophageal cancer has also been widely studied." (PMID 35989326, 2022). "Our research comprehensively investigates the anti-tumor effect of CUDC-907 in vitro and in vivo, suggesting the efficacious inhibition of CUDC-907 on the proliferation, migration, and invasion of esophageal cancer cells and the induction autophagy via mTOR inhibition and LCN2 downregulation." (PMID 35989326, 2022). "Several nucleoproteins (MISP, KLF10, KLF15, PPP1R18, and RXRβ) have been identified by affinity chromatography and mass spectrometry and could respond to TPA stimulation and regulate LCN2 expression in esophageal cancer cells." (PMID 29098164, 2017). "Based on LCN2/LOXL2, LCN2/MMP9 and LOXL2/MMP9 protein–protein interactions, we further elucidated the molecular and cellular mechanisms underlying the LCN2/LOXL2/MMP9 ternary complex that promoted migration and invasion of oesophageal cancer cells, playing a synergistic role." (PMID 37753805, 2023). "Furthermore, this drug could downregulate LCN2 expression in esophageal cancer cells and increase the accumulation of intracellular ROS levels to activate the ER stress response, resulting in a significant increase in autophagy, followed by tumor cell death." (PMID 35989326, 2022). "The endogenous expression level of LCN2 and LOXL2 was examined in eight oesophageal cancer cell lines, with human 293T as a control." (PMID 37753805, 2023).
esophageal cancer (continued). "LCN2, LOXL2, and MMP9 formed a ternary complex in oesophageal cancer cells, but the biological function of the ternary complex remained to be explored." (PMID 37753805, 2023). "The SRCR structure is a key domain through which LOXL2 interacts with both LCN2 and MMP9 to play an important biological role in oesophageal cancer." (PMID 37753805, 2023). "Considering the crosstalk of functional roles of LCN2, MMP9 and LOXL2 in tumour progression, we hypothesized that an LCN2/LOXL2/MMP9 ternary complex might exist in oesophageal cancer and play a synergistic role in biological function." (PMID 37753805, 2023). "The LCN2/LOXL2/MMP9 complex remodels the ECM and activates the FAK/AKT/GSK3β signalling pathway to enhance SPOCK1 expression, promoting the migration and invasion of oesophageal cancer cells." (PMID 37753805, 2023). "Moreover, both Transwell assays and invasion assays showed that overexpression of LCN2/LOXL2, LCN2/MMP9 and LOXL2/MMP9 enhanced the migration and invasion of oesophageal cancer cells." (PMID 37753805, 2023). "Therefore, LCN2/LOXL2/MMP9 activated the FAK/AKT/GSK3β signalling pathway to enhance SPOCK1 expression and remodel the ECM, thus promoting the migration and invasion of oesophageal cancer cells." (PMID 37753805, 2023). "Moreover, we found LCN2 could be induced by the tumor-promoting agent 12-O-tetradecanoylphorbol-13-acetate (TPA), in esophageal cancer cells at the transcriptional level." (PMID 29098164, 2017).